HOXD10 (homeobox D10)
Diseases named in the same sentence as HOXD10 in open-access papers (continued):
Sharing a sentence is not in itself a finding about the gene and the disease.
gastric cancer (9 papers, 2013 to 2023). A primary or metastatic malignant neoplasm involving the stomach. "In gastric carcinoma HOXD10 is downregulated and its forced expression is associated with reduced proliferation, invasion, migration and tumor growth." (PMID 25301728, 2014). "miR10a promotes gastric cancer cell invasion through repression of HOXD10 expression that results in up-regulation of RHOC expression and activation of the AKT signaling pathway." (PMID 37582765, 2023). "HOXD10 has been demonstrated to act as a transcription factor targeting the promoter region of IGFBP3 in gastric cancer." (PMID 29075359, 2017). "In conclusion, we analyzed the expression of miR-10b in gastric cancer cell lines, and the effect of miR-10b on cell proliferation, migration, invasion assays, and Hoxd10 expression." (PMID 26311318, 2015). "Hoxd10 was overexpressed in gastric cancer and correlated with size of tumor, Lauren classification, depth of invasion, lymph node and distant metastasis, TNM stage, and prognosis." (PMID 26311318, 2015). "Hoxd10 was highly expressed in gastric cancer and correlated with size of tumor, Lauren classification, depth of invasion, lymph node and distant metastasis, Tumor-Node-Metastasis (TNM) stage, and prognosis." (PMID 26311318, 2015). "Hoxd10 was upregulated in 82 (89.13 %) normal gastric mucosa samples, and in 242 of 436 (55.5 %) cases of gastric cancer." (PMID 26311318, 2015). "Results reported here increase the understanding of the molecular basis of miR-10b in gastric cancer and suggest that miR-10b promotes migration and invasion through Hoxd10 in human gastric cancer cell lines." (PMID 26311318, 2015). "The study revealed that lymph node (P = 0.012) and distant metastases (P = 0.008), TNM stage (P = 0.001), and expression of Hoxd10 (P = 0.008) were independent prognostic factors in patients with gastric carcinoma." (PMID 26311318, 2015). "Exogenous HoxD10 significantly enhanced the activity of luciferase reporter containing these binding regions in gastric cancer cells." (PMID 24386080, 2013). "Genome-wide analysis has been carried out to screen the downstream genes of HoxD10 during spinal cord development and in gastric cancer cells." (PMID 24386080, 2013). "Collectively, above results indicate that IGFBP3 is a direct target of HoxD10 in gastric cancer cells." (PMID 24386080, 2013). "Here, we found that the expression of IGFBP3 were upregulated after ectopic expression of HoxD10 in gastric cancer cells." (PMID 24386080, 2013). "Our studies provided first evidence to show that HoxD10 directly binds the IGFBP3 promoter to activate the expression of IGFBP3 in gastric cancer cells." (PMID 24386080, 2013). "We have previously presented that homeobox D10 (HoxD10) served as a tumor suppressor by suppressing tumor growth and invasiveness, which was epigenetically silenced in gastric cancer." (PMID 24386080, 2013). "As expected, the expression level of IGFBP3 mRNA and protein were upregulated by forced expression of HoxD10 in different gastric cancer cell lines." (PMID 24386080, 2013). "Genome-wide analysis revealed that multiple genes including IGFBP3 were regulated by HoxD10 in gastric cancer cells in our previous study." (PMID 24386080, 2013). "Another pivotal study showed that the mRNA expression level of HOXD10 in stomach cancer tissues was remarkably lower than that in normal surrounding tissues, and the aberrant reduction of HOXD10 expression promoted migration and invasion in gastric cancer cells." (PMID 34825321, 2022). "According to Wang and colleagues 24, HOXD10 is downregulated in gastric cancer tissues and cell lines compared with normal tissues, suggesting that high expression of HOXD10 impaired cell migration and invasion, which may function as tumor suppressor." (PMID 28745433, 2017). "miR-10b promotes migration and invasion through Hoxd10 in human gastric cancer cell lines and may play an important role in tumorigenesis, progression, and prognosis." (PMID 26311318, 2015).
gastric cancer (continued). "Taken together, these data suggested that HoxD10 could transcriptionally upregulate the expression of IGFBP3 in gastric cancer cells." (PMID 24386080, 2013). "Our previous report revealed that insulin-like growth factor binding protein-3 (IGFBP3) was regulated by HoxD10 in gastric cancer cells; however, the functional roles and underlying mechanisms of IGFBP3 in gastric cancer remain unclear." (PMID 24386080, 2013). "To determine whether HoxD10 could transcriptionally regulate the expression of IGFBP3 in gastric cancer cells, we observed the expression level of IGFBP3 after stably introducing HoxD10 gene into BGC823 and SGC7901 cells, or transiently knocking down of HoxD10 in HGC27 cells." (PMID 24386080, 2013). "Thus, our data suggest that HoxD10-targeted gene IGFBP3 may suppress gastric cancer cell invasion and favors the survival of gastric cancer patients." (PMID 24386080, 2013). "HOXD10 targeted the IGFBP3 gene promoter region and upregulated its expression in gastric cancer." (PMID 29075359, 2017). "In the present study, we identified that HoxD10 could directly bind the promoter regions of IGFBP3 potentially via the TTAT element, thus transcriptionally regulates its expression in gastric cancer." (PMID 24386080, 2013). "We have systematically screened the potential targets of HoxD10 by cDNA microarray and identified multiple genes, including insulin-like growth factor binding protein-3 (IGFBP3) that might be responsible for the tumor suppressing effect of HoxD10 in gastric cancer." (PMID 24386080, 2013). "Considering promoter region of IGFBP3 has several potential binding sites for HoxD10, predicted by PROMO, a program for the prediction of transcription factor binding sites, HoxD10 might directly interplay with IGFBP3 in the regulation of gastric cancer cell invasion." (PMID 24386080, 2013).
colon carcinoma (8 papers, 2019 to 2025). "For example, HOXD10 overexpression in colon cancer inhibits the RHOC/AKT/MAPK pathway, thereby suppressing cell proliferation, migration, and invasion." (PMID 40148674, 2025). "In vitro colon cancer cell lines exhibited the same pattern of HOXD10 hypermethylation subsequent to mRNA repression." (PMID 39858044, 2025). "Colon carcinomas show an overexpression of HOXD10 which distinguishes colonic stem cells from colon carcinoma cells." (PMID 38907278, 2024). "HOXD10 has been widely acknowledged as a tumor suppressor and has been observed to be downregulated in various cancer types, including colon carcinomas, early-stage head and neck squamous cell carcinoma, and oral squamous cell carcinoma." (PMID 38138552, 2023). "The demethylation of HOXD10 after treatment with 1 μM demethylation agent for 72 h in colon carcinoma was analyzed using RT-PCR." (PMID 30683109, 2019). "The role of posterior HOXD genes in colon cancer is not well defined; HOXD8 and HOXD12 expression are reduced in colon cancer, whereas HOXD10 expression may be increased." (PMID 35015732, 2022). "However, the methylation status of HOXD10 and mechanism of action in colon cancer with RHOC and AKT pathway are still unclear." (PMID 30683109, 2019). "The expression of HOXD10 and RHOC was revealed by immunohistochemistry in disparate differentiation colon carcinoma tissues, and the dephosphorylation of AKT and MAPK pathways were detected by RT-PCR and western blot." (PMID 30683109, 2019). "HOXD10 was suppressed in colon adenocarcinoma cells, which down-regulated RHOC/AKT/MAPK pathway to enhance colon cancer cells apoptosis and constrain the proliferation, migration and invasion." (PMID 30683109, 2019). "HOXD10 was inhibited in colon adenocarcinoma cells, thereby downregulating the RHOC/AKT/MAPK pathway to enhance apoptosis and restrain proliferation, migration, and invasion of colon cancer cells." (PMID 36213580, 2022). "The normal peripheral lymphocytes DNA which served as negative control were included for each PCR.HOXD10 were confirmed hypermethylation in colon cancer cell lines SW480,LOVO and LS180 compared with normal colon cell line CCD18-Co." (PMID 30683109, 2019).
hepatocellular carcinoma (8 papers, 2015 to 2025). A malignant tumor that arises from hepatocytes. "Other notable promoters were those of Hoxd10, a tumor suppressor gene whose promoter hypermethylation has been linked to hepatocellular carcinoma, and Thy1 whose expression stimulates liver regeneration." (PMID 35235716, 2022). "In hepatocellular carcinoma, HOXD10 has been shown to inhibit proliferation by suppressing the ERK signaling pathway." (PMID 40148674, 2025). "The function and regulation of HOXD10 remain unclear in human hepatocellular carcinoma (HCC)." (PMID 29075359, 2017). "HOXD10 is a member of the HOX gene family and is abnormally expressed in several cancers, such as cholangiocellular cancer (CCC) and hepatocellular cancer." (PMID 34825321, 2022).
oral cancer (6 papers, 2012 to 2025). "While these findings suggest that HOXD10 has tumor-suppressive functions for mammary epithelial cells, a different scenario is observed for esophageal and oral cancer." (PMID 22227861, 2012). "Moreover, after the treatment with a DNA methyltransferase inhibitor 5-Aza-2′-deoxycytidine, the methylation degree of HOXD10, which was correlated with decreased transcript expression, was restored in oral cancer cell lines." (PMID 30683109, 2019). "In contrast, HOXA7, HOXA10, HOXB7, HOXC6, HOXC10, HOXD10, and HOXD11 were consistently upregulated in potentially malignant oral lesions as they advanced to oral cancer." (PMID 41477365, 2025). "HOXA7, HOXA10, HOXB7, HOXC6, HOXC10, HOXD10, HOXD11 showed consistent upregulation in the potentially malignant oral lesions through their progression to oral cancer, which indicated the posterior prevalence of the HOX genes during cancer progression." (PMID 35710803, 2022). "Overall our results suggest that HOXD10 and HOXD11 act as oncogenes in oral cancer, whereas previous reports have indicated that they act as tumor suppressors." (PMID 25301728, 2014).
breast tumor (5 papers, 2012 to 2018). "Downregulation of c-Src/Twist or inhibition of miR-10b production results in HOXD10 upregulation and causes a decrease in the expression of RhoA/RhoC and a reduction of ROK-mediated breast tumor cell invasion." (PMID 27070574, 2016). "Also, after restoring HOXD10 expression in malignant breast tumor cells, cell migration was significantly impaired and their ability to form tumors in mouse xenografts was inhibited." (PMID 22227861, 2012). "Twist overexpression promotes a cancer stem cell (CSC) phenotype and has also been shown to induce miR-10b, which inhibits the mRNA of HOXD10 and results in the increase of RhoC in CD44-positive breast tumor cells." (PMID 27070574, 2016). "These events lead to the reduction of the tumor suppressor protein, HOXD10, RhoA/RhoC overexpression, ROK activation, and breast tumor cell invasion." (PMID 27070574, 2016). "We found that all ten EMT-related genes were frequently methylated in primary breast tumours, i.e. CLDN18 (100 %), KRT85 (100 %), MIR127 (100 %), MIR433 (100 %), MIR23b (60 %), KRT83 (100 %), MST1R (60 %), BVES (60 %), CLDN6 (50 %) and HOXD10 (55 %)." (PMID 26052355, 2015).
head and neck cancer (5 papers, 2014 to 2024). A primary or metastatic malignant neoplasm affecting the head and neck. "HOXD10 overexpression has been reported to induce cancer cell proliferation, while low expression induced invasion and metastases in head and neck cancer cell lines, supporting the proliferative role of HOXD10 in cancer." (PMID 38745021, 2024). "Additional studies are warranted to fully evaluate the potential of HOXD10 as a target or prognostic tool in head and neck cancers." (PMID 25301728, 2014). "Additional studies are now warranted to fully evaluate HOXD10 as a prognostic tool in head and neck cancers." (PMID 25301728, 2014). "Utilizing patient tumor samples a significant association was found between immunohistochemical staining of HOXD10 and both the overall and the disease-specific survival, adding further support that HOXD10 is dysregulated in head and neck cancer." (PMID 25301728, 2014). "POU2F1 activity regulates HOXD10 and HOXD11 to promote proliferative and invasive phenotypes in head and neck cancer." (PMID 36213580, 2022). "For instance, in head and neck cancer, POU2F1 can bind to the promoters of HOXD10 and HOXD11 to activate their transcription, thus promoting tumor progression." (PMID 34257651, 2021).
ovarian carcinoma (5 papers, 2015 to 2025). A malignant neoplasm originating from the surface ovarian epithelium. "Exploring the regulatory pathways and downstream genes associated with HOXD10 provide new biological indicators for the early detection of EOC or novel avenues for treatments of ovarian cancer." (PMID 38356716, 2024). "Therefore, in the present study, a comprehensive analysis was performed to gain insight into the potential underlying genetic alternations related to HOXD10 modification in ovarian cancer using gene expression array and bioinformatics analysis." (PMID 38356716, 2024). "Its overexpression in ovarian cancer tissues and cell lines downregulates the tumor suppressor gene HOXD10, promoting enhanced migration and invasion of ovarian cancer cells driving tumor progression." (PMID 39796267, 2025). "Our results showed that HOXD10 is involved in cancer metabolism and tumor microenvironment in ovarian cancer." (PMID 38356716, 2024). "Thus, we examined the role of HOXD10 in the regulation of ovarian cancer cell proliferation, and migration by introducing HOXD10 plasmid or HOXD10-shRNA." (PMID 38356716, 2024). "Previous studies on ovarian cancer showed that downregulation of HOXD10 expression by miR-10b overexpression may enhance the migration and invasion in ovarian cancer cell lines by inducing an increase in prometastatic gene products." (PMID 34825321, 2022). "Considering the data from ectopic overexpression and the report of a lack of HOXD10 induction after HOTAIR knockdown in ovarian cancer cells, our finding strongly argues that HOTAIR target genes are tissue-specific." (PMID 25994132, 2015). "Downregulation of HOXD10 expression by miR-10b overexpression may induce an increase in prometastatic gene products, such as MMP14 and RHOC, and contribute to the acquisition of a metastatic phenotype by epithelial ovarian cancer cells." (PMID 36213580, 2022).
bladder cancer (4 papers, 2019 to 2024). "Propofol was found to significantly increase both the mRNA and protein expression of HOXD10 in bladder cancer T24 cells." (PMID 37627900, 2023). "In comparison to primary bladder cancer, HOXD10 was downregulated in metastatic bladder cancers." (PMID 37627900, 2023). "HOXD10 is a direct target of miR-10b in bladder cancer cells." (PMID 37627900, 2023). "HOXD10 and KLF4 were identified as direct targets of miR-10b in bladder cancer." (PMID 37627900, 2023). "MMP14 and E-cadherin may be the downstream targets of HOXD10 and KLF4 in the miR-10b-mediated suppression of bladder cancer metastasis." (PMID 37627900, 2023). "Therefore, the inhibition of the miR-10b/HOXD10/MMP14 and miR-10b/KLF4/E-cadherin axes may offer potential therapeutic targets for metastatic bladder cancer." (PMID 37627900, 2023).
endometriosis (4 papers, 2014 to 2024). The growth of functional endometrial tissue in anatomic sites outside the uterine body. "Our previous study showed that overexpression of HOXD10 reverses the low expression of miR-381 in endometriosis-associated clear cell and endometrioid ovarian cancer." (PMID 38356716, 2024). "The most responsive downstream targets, genes at the HOXA and HOXD loci, that associated with elevated HOTAIR in severe endometriosis were HOXD10 and HOXA5." (PMID 33667269, 2021). "Our study identified two major downstream targets, HOXD10 and HOXA5, regulated by HOTAIR in advanced endometriosis and the associated ovarian clear cancer cells." (PMID 33667269, 2021). "Data mining further revealed higher mRNA HOTAIR levels in the endometria of patients with severe endometriosis which consistently showed reduced HOXD10 and HOXA5 levels." (PMID 33667269, 2021). "HOXD10 has been implicated in endometrial stromal cell proliferation, and our pathway analysis comparison identified it as well, suggesting that all of the HOX clusters may show aberrant methylation in endometriosis." (PMID 24603652, 2014). "Our data confirm the molecular link between HOTAIR and those homeobox proteins, suggesting the involvement of HOXD10 and HOXA5 in endometriosis progression." (PMID 33667269, 2021). "Downstream screening using data from clinical and cell-based studies revealed HOXD10 and HOXA5 to be the key regulators for HOTAIR to promote endometriosis progression." (PMID 33667269, 2021). "In addition, our data indicated that functional axes of HOTAIR/HOXD10 and HOTAIR/HOXA5 may play potent roles in regulating endometriosis progression." (PMID 33667269, 2021).
esophageal squamous cell carcinoma (4 papers, 2016 to 2025). Esophageal squamous cell carcinoma (ESCC) is a type of esophageal carcinoma (EC) that can affect any part of the esophagus, but is usually located in the upper or middle third. "HOXD10 was found to act as a tumor suppressor, which inhibited the development of esophageal squamous cell carcinoma through the PI3K/AKT/mTOR pathway, and in another study, expression of the AKT/mTOR signaling pathway was associated with the progression of EC." (PMID 34022794, 2021).
head and neck squamous cell carcinoma (4 papers, 2015 to 2023). A squamous cell carcinoma that arises from any of the following anatomic sites: lip and oral cavity, nasal cavity, paranasal sinuses, pharynx, larynx, and salivary glands. "For instance, HOXD10 and miR-146a are associated with head and neck squamous cell carcinomas, and HOXA1, under the regulation of miR-100, in small-cell lung cancer." (PMID 26565624, 2015). "Knockdown of HOXD10 led to decreased migration and proliferation in head and neck squamous cell carcinoma cells in their study, which suggested that HOXD10 acts as an oncogene that promote metastases." (PMID 28745433, 2017). "According to Sharpe and colleagues 23, HOXD10 and HOXD11 are expressed at high levels in head and neck squamous cell carcinoma, which corresponded to our results." (PMID 28745433, 2017).
lung cancer (4 papers, 2013 to 2023). A malignant neoplasm involving the lung. "For example, miR-224 has a tumor-promoting effect in nonsmall cell lung cancer, pancreatic cancer, and cervical cancer via targeting of homeobox D10 (HOXD10), androgen receptors, thioredoxin-interacting protein (TXNIP), and Ras-association domain family 8 (RASSF8)." (PMID 37534255, 2023). "We did not detect HOXD10 expression in lung cancer, and there have been no previous reports regarding HOXD10 expression and lung cancer." (PMID 24216130, 2013).
clear cell renal cell carcinoma (3 papers, 2022 to 2024). "In renal clear cell carcinoma, HOXD10 acts as a tumor suppressor to inhibit invasion and migration of cancer cells by modulating E-cadherin and EMT." (PMID 39759007, 2024). "Demethylation or overexpression of HOXD10 has been shown to suppress proliferation and migration, and to promote apoptosis in CRC, which may be related to its ability to bind E-cadherin upstream sequences and positively regulate E-cadherin expression, as described in clear cell renal cell carcinoma." (PMID 39125691, 2024).